MLLT1 (MLLT1 super elongation complex subunit)
Description:
Chromatin reader component of the super elongation complex (SEC), a complex required to increase the catalytic rate of RNA polymerase II transcription by suppressing transient pausing by the polymerase at multiple sites along the DNA. Specifically recognizes and binds acetylated and crotonylated histones, with a preference for histones that are crotonylated. Has a slightly higher affinity for binding histone H3 crotonylated at 'Lys-27' (H3K27cr) than 'Lys-20' (H3K9cr20). May play a role in leukemogenic gene transcription. Acts as a key chromatin reader in acute myeloid leukemia by recognizing and binding to acetylated histones via its YEATS domain, thereby regulating oncogenic gene transcription.
Synonyms: ENL; LTG19; YEATS1
Tractability: Small molecule: a structure with a bound ligand is known; a high-quality ligand is known. PROTAC: UniProt records ubiquitination sites on it; ubiquitination databases record sites on it; its protein half-life has been measured; a small molecule that binds it is known.
Target class: YEATS domain; Epigenetic regulator; Reader
Chemical probes: NVS-MLLT-1 (high quality), PFI-6 (high quality), PFI-8 (high quality), SGC-iMLLT (high quality), SR-0813 (high quality)
Gene: Protein-coding gene on chromosome 19 (6,210,377 to 6,279,975, reverse strand). Ensembl gene ENSG00000130382.
Subcellular location: Nucleus
Subcellular location (Human Protein Atlas): Nucleoplasm; Nucleoli fibrillar center
Pathways (Reactome):
Gene expression (Transcription): Formation of RNA Pol II elongation complex; RNA Polymerase II Pre-transcription Events; RNA Polymerase II Transcription Elongation
Gene Ontology:
Molecular function: protein binding; chromatin binding
Biological process: positive regulation of DNA-templated transcription
Cellular component: fibrillar center; nucleoplasm; transcription elongation factor complex; nucleus
Genetic constraint (gnomAD): Loss-of-function variants: 11 observed, 48.03 expected, observed/expected ratio (o/e) 0.23, 90% interval 0.14 to 0.38. The upper end of that interval is the gene's LOEUF score, 0.38, which puts it in group 1 of 6, group 1 being the genes least tolerant of losing a copy. Missense variants: 512 observed, 705.8 expected, observed/expected ratio (o/e) 0.73, 90% interval 0.67 to 0.78. Synonymous variants: 313 observed, 298.08 expected, observed/expected ratio (o/e) 1.05, 90% interval 0.96 to 1.15.
Homologues: Orthologues: chimpanzee MLLT1 (99% identical), macaque MLLT1 (99% identical), pig MLLT1 (91% identical), dog MLLT1 (89% identical), guinea pig MLLT1 (86% identical), mouse Mllt1 (86% identical), rat Mllt1 (86% identical), tropical clawed frog mllt1 (74% identical), zebrafish mllt1a (70% identical), Drosophila melanogaster ear (37% identical). Paralogues in human: MLLT3 (55% identical), YEATS2 (25% identical).
Diseases named in the same sentence as MLLT1 in open-access papers:
MLLT1 is named in the same sentence as 36 diseases in open-access papers, as found by Europe PMC text mining. Sharing a sentence is not in itself a finding about the gene and the disease. The quoted sentences say what the papers report.
leukemia (45 papers, 2008 to 2025). A malignant (clonal) hematologic disorder, involving hematopoietic stem cells and characterized by the presence of primitive or atypical myeloid or lymphoid cells in the bone marrow and the blood. "Notably, both the non-rearranged allele of Kmt2a and Mllt1 as well as the reciprocal product Mllt1-Kmt2a fusion were also expressed in the leukemia cells." (PMID 33134860, 2020). "Among the altered genes, ARHGAP26 and MLLT1 have been associated with leukemia-specific translocations, DDHD2, FGFR1 and PTPN1 have tumor-promoting potential in breast cancer, and CTNNA3 may promote tumor formation in urothelial cancer." (PMID 20428235, 2010). "We firstly cloned several individual sgRNAs targeting the equivalent introns of Kmt2a and Mllt1 that are orthologue regions in the human leukemia translocation." (PMID 33134860, 2020). "Post-mortem examination of Kmt2a-Mllt1 mice confirmed the development of leukemia with predominant myeloblasts in the peripheral blood, splenomegaly and extensive infiltration of leukocytes into peripheral organs such as liver and kidneys." (PMID 33134860, 2020). "The identical MLLT1 insertion variant was not identified in other tumors (neuroblastoma, lymphoma, leukemia, and osteosarcoma), and copy number loss at chromosome 19p13 was not identified." (PMID 39687897, 2024). "We delineate ontogenically conserved and developmentally regulated molecular events in MLL::Eleven Nineteen Leukemia (ENL/MLLT1)-mediated transformation and provide evidence for an age-dependent difference in leukemia cell phenotype mediated by cell-intrinsic as well as niche-associated factors." (PMID 38555405, 2024). "MLLT1 is a known fusion partner in MLL-rearranged leukemias; although no fusion was identified here, its mutation may signal an underlying predisposition to hematologic neoplasia." (PMID 41488087, 2025). "Although MLL fuses with a variety of partners, most MLL fusion-mediated leukemia cases are caused by the fusions with the AF4 family (e.g., AF4 also known as AFF1, AF5Q31 also known as AFF4) and ENL family (e.g., ENL also known as MLLT1, AF9 also known as MLLT3)." (PMID 34431785, 2021). "We also detected the signature in some patients with KMT2A::MLLT1 or KMT2A::MLLT3 rearrangements, suggesting that the signature can be broadly applicable to KMT2A rearranged leukemia." (PMID 40646135, 2025). "To validate the requirement of immunoproteasome function for leukemia development, we used a Doxycycline (DOX) inducible mouse model of KMT2A:: MLLT1 (i- KMT2A::MLLT1)." (PMID 38049829, 2023). "KMT2A (MLL) rearrangements are observed in various types of pediatric and adult leukemia, but only one adult case report has so far shown KMT2A (MLL)-MLLT1 gene rearrangements in blastic plasmacytoid dendritic cell neoplasm (BPDCN)." (PMID 34996478, 2022).
acute myeloid leukemia (7 papers, 2016 to 2025). Acute myeloid leukemia (AML) is a group of neoplasms arising from precursor cells committed to the myeloid cell-line differentiation. "In acute myeloid leukemia, MLLT1 regulates chromatin remodeling and gene expression of many important proto-oncogenes." (PMID 34071989, 2021).
Wilms tumor (6 papers, 2015 to 2025). An embryonal neoplasm characterized by the presence of epithelial, mesenchymal, and blastema components. "In this case, we report the recurrence of nephroblastoma with MLLT1 gene mutation and review relevant literature." (PMID 39687897, 2024). "Through whole genome sequencing of pathological tissues from 82 recurrent nephroblastoma cases, the proportion of MLLT1 hotspot mutations was 6.1%, including two in the discovery set (n = 51) and three in the validation set (n = 31)." (PMID 39687897, 2024). "MLLT1 (ENL) mutation can drive nephroblastoma by enhancing the phase separation and transcription of target genes." (PMID 39687897, 2024). "We conclude that activating MLLT1 mutations accompanied by Wnt activation early in renal development result in the development of Wilms tumour." (PMID 26635203, 2015). "Here we identify recurrent mutations within Wilms tumours that involve the highly conserved YEATS domain of MLLT1 (ENL), a gene known to be involved in transcriptional elongation during early development." (PMID 26635203, 2015). "In this study, the authors identify somatic mutations of the MLLT1 gene that are potentially involved in the aetiology of a subset of Wilms tumours." (PMID 26635203, 2015). "Small, in-frame INDEL mutations in the YEATS domain of MLLT1 were first identified in Wilms tumors." (PMID 40395503, 2025). "We report two cases of a second recurrence of nephroblastoma with MLLT1 mutation." (PMID 39687897, 2024). "MLLT1 mutations in nephroblastoma can also mediate HOX disorders." (PMID 39687897, 2024). "MLLT1 gene is a newly discovered gene likely associated with the pathogenesis of nephroblastoma." (PMID 39687897, 2024). "Further understanding the function of MLLT1 mutations in nephroblastoma could provide significant insight into the development of nephrogenic rests and risk factors for tumor relapse." (PMID 39687897, 2024). "Hence, it may be speculated that the patients carrying MLLT1 mutations may present at a younger age, are more likely to develop multi-foci multiple intralobar nephrogenic rests, and have a higher risk of nephroblastoma." (PMID 39687897, 2024). "Recently, a series of hot spot mutations in the YEATS domain of ENL, also known as MLLT1, have been identified in 5%–9% of nephroblastoma patients, making it the most frequently mutated epigenetic regulator in the disease." (PMID 39687897, 2024). "In addition to genetic changes identified within recurrent nephroblastoma, research has identified mutations that involve the highly conserved YEATS domain of MLLT1, a gene known to be involved in transcriptional elongation during early development." (PMID 39687897, 2024).
acute leukemia (5 papers, 2019 to 2026). A clonal (malignant) hematopoietic disorder with an acute onset, affecting the bone marrow and the peripheral blood. "The most frequently found fusion partners of KMT2A in acute leukemia are the C‐terminal parts of AFF1, MLLT3, MLLT1 and MLLT10." (PMID 39887730, 2026).
glioblastoma (3 papers, 2018 to 2023). The most malignant astrocytic tumor (WHO grade IV). "In cancer stem cells of glioblastoma (GBM), there is a potentially harmful frameshift mutation in the MLLT1 gene, which occurs only in cancer stem cell samples derived from peritumoral tissues." (PMID 37664112, 2023).
myeloid leukemia (3 papers, 2015 to 2020). A clonal proliferation of myeloid cells and their precursors in the bone marrow, peripheral blood, and spleen. "Notably, the Kmt2a-Mllt1 myeloid leukemia can be established in the Pax5 +/− background with similar dynamics as in the Pax5 +/+ background confirming that a reduced Pax5 gene dosage does not influence the leukemogenic activity of Kmt2a-Mllt1." (PMID 33134860, 2020).
developmental delay (2 papers, 2016 to 2019). "The proband (BAB6950) in family 058 with a potentially deleterious homozygous variant in MLLT1 presents with developmental delay, hypotonia, infantile spasm, and cortical dysgenesis." (PMID 27435318, 2016).
chronic lymphocytic leukemia (1 paper, 2012). "Recently, the CDK9 inhibitor flavopiridol was shown to induce apoptosis in primary chronic lymphocytic leukemia by targeting CDK9, cyclin T1, AFF3/4 and MLLT1." (PMID 23140174, 2012).
COVID-19 (1 paper, 2023). A disease caused by infection with severe acute respiratory syndrome coronavirus 2. "Among these TFs-genes, HDGF, SUPT5H and MLLT1 with 4 edges was considered as key TF-genes which was highly related with regulation of T cell differentiation in elderly COVID-19 patients." (PMID 36966292, 2023). "The TFs-genes network showed that HDGF, SUPT5H and MLLT1, with the most edges, played important roles in age-related processes of COVID-19." (PMID 36966292, 2023).
endometriosis (1 paper, 2023). The growth of functional endometrial tissue in anatomic sites outside the uterine body. "We have shown that primary ectopic stroma cells of women with endometriosis, expressing lower levels of MLLT1 and higher levels of ACTA2, compared to primary cells of women without the disease, displayed increased adhesive properties." (PMID 38203610, 2023). "Women with severe stage endometriosis (the revised American Fertility Society (rAFS) score III + IV) showed significantly lower levels of MLLT1 expression compared to women without the disease (0.53 median fold change, adjp value = 0.045)." (PMID 38203610, 2023).
esophageal cancer (1 paper, 2023). A primary or metastatic malignant neoplasm involving the esophagus. "CTCF, MLLT1, and TGIF2 are transcriptional regulators that play crucial roles in the transcription of important proto-oncogenes such as FOXM1, MYC, HoxA gene family, and OCT4 in multiple cancer types including HCC, esophageal cancer, and lung adenocarcinoma." (PMID 37335919, 2023).
glioma (1 paper, 2022). A benign or malignant brain and spinal cord tumor that arises from glial cells (astrocytes, oligodendrocytes, ependymal cells). "From these findings, we hypothesize that MLLT1 may be of importance in stem cell differentiation/glioma pathogenesis." (PMID 34996478, 2022).
mesothelioma (1 paper, 2021). A usually malignant and aggressive neoplasm of the mesothelium which is often associated with exposure to asbestos. "Yoshikawa and colleagues suggested that mesothelioma may be the consequence of the somatic inactivation of chromatin-remodeling complexes and/or histone modifiers, including MLLT1." (PMID 34071989, 2021).
papillary thyroid carcinoma (1 paper, 2020). "We found that cg00768487 (UBXN11) and cg03110787 (MLLT1) have been associated with papillary thyroid carcinoma, cg10806146 (SLC20A2) and cg15936066 (SLC20A2) with prostate cancer, cg15936066 (SLC20A2) with systemic lupus erythematosus, and cg07538190 (C8orf58) with psoriasis." (PMID 32493484, 2020).
Salmonella Infections (1 paper, 2022). Infections with bacteria of the genus SALMONELLA. "For the G2 group, the main pathways were: Salmonella infection (NFKB1, TJP1, DYNC2H1), transcriptional misregulation in cancer (MET, MLLT1, NFKB1), and adherens junction (MET, TJP1)." (PMID 36012418, 2022).
tumor (15 papers, 2010 to 2025). "Of MLLT1-wild-type tumours, 23 and 21% were associated with ILNRs and PLNRs, respectively; in contrast, 10/19 (53%, P=0.011) MLLT1-mutant tumours arose in ILNRs, and 0/19 (P=0.019) arose in PLNRs (Fisher's exact test)." (PMID 26635203, 2015). "We were unable to identify any evidence of MLLT1 germline mutations, even in the MLLT1-mutant tumours with multiple ILNRs." (PMID 26635203, 2015). "Sufficient DNA was available on 16/19 MLLT1-mutant tumours to perform mutation analysis for WT1, CTNNB1, WTX, DROSHA, DGCR8, and SIX1/2 and this revealed five CTNNB1 mutations, one WTX mutation, and no WT1 DROSHA, DGCR8, or SIX1/2 mutations." (PMID 26635203, 2015). "PCR amplification followed by sequencing identified an additional MLLT1 p.117_118insNHL mutation in 1/19 tumours originally characterized by WES, for a total of 7 MLLT1 mutations in 77 discovery set tumours (11%)." (PMID 26635203, 2015). "MLLT1 insertion or deletion mutations were found in 19/475 tumours (4%)." (PMID 26635203, 2015). "The tumor gene analysis detected nine nucleotide in-frame insertions (TTCACCT GC) at MLLT1 position c.352_353 (p.L117_R118insLHL) of the NM_005934.4 with a mutation frequency of 47.50%." (PMID 39687897, 2024). "The tumor gene analysis detected nine nucleotide in-frame insertions (AACCACCTG) at MLLT1 position c.351_352 (p.R118delinsNHLR) of the NM_005934, with a mutation frequency of 49.40%." (PMID 39687897, 2024). "Four MLLT1-mutant tumours arose in kidneys with multiple ILNRs, a feature thus far predominantly recognized in patients with syndromes associated with germline WT1 mutations." (PMID 26635203, 2015). "Patients with MLLT1-mutant tumours present at a younger age and have a high prevalence of precursor intralobar nephrogenic rests." (PMID 26635203, 2015). "Of note, in 5/7 MLLT1-mutant tumours in the discovery set, the comparator constitutional sample was adjacent normal kidney and lacked the mutation." (PMID 26635203, 2015). "An insertion in MLLT1 was also maintained in the primary and relapsed tumor." (PMID 40439002, 2025). "MLL gene is made up of 14 exons, encoding the histone lysine methyltransferase whereby it is also called KMT2A, which harbors powerful transforming potential associated with neoplastic diseases assisted by specific partners, such as AF9 (MLLT3), AF4, and ENL (MLLT1)." (PMID 34540702, 2021). "We report in-frame insertion/deletion MLLT1 mutations in FHWT that are absent in other TARGET paediatric tumour types." (PMID 26635203, 2015). "A different prevalence of other genetic markers was identified in MLLT1-mutant tumours." (PMID 26635203, 2015). "The absence of reports of these novel MLLT1 mutations in other tumours or tissues suggests the possibility that their impact may be restricted to a specific cellular context." (PMID 26635203, 2015). "Moreover, MLLT1-mutant tumours show an increase in MYC gene expression and HOX dysregulation." (PMID 26635203, 2015). "Nor were we able to identify MLLT1 mutations in normal kidney adjacent to MLLT1-mutant tumours." (PMID 26635203, 2015). "Our data indicates that understanding the function of these MLLT1 mutations could provide important insight into the function of the YEATS domain in other proteins, and into transcriptional regulation during early renal development as well as tumour development." (PMID 26635203, 2015). "Gene expression analysis was available for 75 of the 77 tumours (one MLLT1-mutant tumour and one MLLT1 wild-type tumour did not pass quality control)." (PMID 26635203, 2015). "Two tumours with MLLT1 mutations also had CTNNB1 mutations; no MLLT1-mutant tumours had accompanying WT1, WTX, DROSHA, DGCR8, SIX1, or SIX2 mutations." (PMID 26635203, 2015). "Information regarding 1p and 16q LOH analysis performed prospectively during the protocol was available for 11/19 MLLT1-mutant tumours, and neither was found." (PMID 26635203, 2015).
tumor (continued). "Six MLLT1-mutant tumours and six randomly selected MLLT1-wild-type FHWTs were analysed by quantitative reverse transcription PCR, which confirmed increased expression of both HOXA13 and HOTTIP in MLLT1-mutant tumours." (PMID 26635203, 2015). "Copy number loss at 19p13 (the chromosomal location of MLLT1) was not identified in any of the 77 FHWT; five non-mutant tumours had gain of 19p13 due to gain of all or the majority of chromosome 19." (PMID 26635203, 2015). "The aneuploidic increases in copy number of genes that may promote tumor formation, including ARHGAP26, GRB10, DDHD2, FGFR1, CTNNA3, PTPN1 and MLLT1 in the apparently stable and karyotypically normal lines HS293 and HS401, are cause for concern." (PMID 20428235, 2010). "Interestingly, expression of most of the fusion partners including the high‐frequency partners like AFF1, MLLT1, MLLT3, MLLT10, ELL, and MLLT4, were positively correlated with MLL1 expression irrespective of the tumor type." (PMID 30548174, 2019).
cancer (14 papers, 2016 to 2025). A tumor composed of atypical neoplastic, often pleomorphic cells that invade other tissues. "Continuing with the discussion, MLLT1 is an acetyl/acyl-dependent epigenetic reader domain, the dysfunction of which has been implicated in the development of some aggressive cancers." (PMID 37664112, 2023).
MLLT1 also shares sentences with these, for which no sentence is quoted: blood cancer (2 papers); neuroblastoma (2); osteosarcoma (2); pediatric neoplasms (2); acute lymphoblastic leukemia (1); breast carcinoma (1); hematologic diseases (1); Huntington disease (1); infantile spasms (1); lung adenocarcinoma (1); lymphoma (1); overgrowth syndrome (1); pancreatic cancer (1); pediatric kidney cancer (1); prostate carcinoma (1); psoriasis (1); Sepsis (1); systemic lupus erythematosus (1); T-cell acute leukemia (1).